FAM66A (family with sequence similarity 66 member A)
Synonyms: FAM86B2-DT
Gene: Long non-coding RNA gene on chromosome 8 (12,362,019 to 12,625,014, forward strand). Ensembl gene ENSG00000227888.
Diseases named in the same sentence as FAM66A in open-access papers:
FAM66A is named in the same sentence as 1 disease in open-access papers, as found by Europe PMC text mining. Sharing a sentence is not in itself a finding about the gene and the disease.
FAM66A shares sentences with these, for which no sentence is quoted: prostate (1 paper).